HSF2BP (heat shock transcription factor 2 binding protein)
Description:
Meiotic recombination factor component of recombination bridges involved in meiotic double-strand break repair. Modulates the localization of recombinases DMC1:RAD51 to meiotic double-strand break (DSB) sites through the interaction with BRCA2 and its recruitment during meiotic recombination (By similarity). Indispensable for the DSB repair, homologous synapsis, and crossover formation that are needed for progression past metaphase I, is essential for spermatogenesis and male fertility (By similarity). Required for proper recombinase recruitment in female meiosis (By similarity). Inhibits BNC1 transcriptional activity during spermatogenesis, probably by sequestering it in the cytoplasm (By similarity). May be involved in modulating HSF2 activation in testis.
Synonyms: MEILB2; POF19
Tractability: PROTAC: UniProt records ubiquitination sites on it; ubiquitination databases record sites on it.
Gene: Protein-coding gene on chromosome 21 (43,529,186 to 43,659,504, reverse strand). Ensembl gene ENSG00000160207.
Subcellular location: Cytoplasm; Chromosome
Subcellular location (Human Protein Atlas): Nucleoplasm; Cytosol
Gene Ontology:
Molecular function: protein binding
Biological process: double-strand break repair involved in meiotic recombination; female meiosis I; male meiosis I; spermatogenesis; transcription by RNA polymerase II
Cellular component: chromosome; cytosol; nucleoplasm; cytoplasm
Genetic constraint (gnomAD): Loss-of-function variants: 23 observed, 25.92 expected, observed/expected ratio (o/e) 0.89, 90% interval 0.64 to 1.26. The upper end of that interval is the gene's LOEUF score, 1.26, which puts it in group 5 of 6, group 1 being the genes least tolerant of losing a copy. Missense variants: 271 observed, 282.33 expected, observed/expected ratio (o/e) 0.96, 90% interval 0.87 to 1.06. Synonymous variants: 94 observed, 104.21 expected, observed/expected ratio (o/e) 0.9, 90% interval 0.76 to 1.07.
Homologues: Orthologues: chimpanzee HSF2BP (99% identical), macaque HSF2BP (97% identical), dog HSF2BP (92% identical), pig HSF2BP (91% identical), mouse Hsf2bp (88% identical), rat Hsf2bp (88% identical), guinea pig HSF2BP (87% identical), rabbit HSF2BP (77% identical), tropical clawed frog hsf2bp (50% identical), zebrafish hsf2bp (45% identical).
Diseases named in the same sentence as HSF2BP in open-access papers:
HSF2BP is named in the same sentence as 20 diseases in open-access papers, as found by Europe PMC text mining. Sharing a sentence is not in itself a finding about the gene and the disease. The quoted sentences say what the papers report.
male infertility (3 papers, 2020 to 2023). The inability of the male to effect fertilization of an ovum after a specified period of unprotected intercourse. "However, most of the current reports on HSF2BP mutations focus on male infertility, while only a few reports of HSF2BP mutations resulting in female reproductive disorders." (PMID 37430352, 2023). "Knockout of Meiok21 decreases the numbers of HSF2BP and DMC1/RAD51 foci, disrupting DSB repair, synapsis and crossover recombination and finally causing male infertility." (PMID 32463460, 2020). "Inactivation of the hsf2bp gene in mice leads to male infertility." (PMID 36167792, 2022).
Ovarian Insufficiency (2 papers, 2020 to 2021). "Our results provide insights into the molecular mechanism of HSF2BP-S167L in human ovarian insufficiency and sub(in)fertility." (PMID 32845237, 2020).
amenorrhea (1 paper, 2021). The absence of menses in a woman who has achieved reproductive age. "Patient POI-1, who carried HSF2BP p.C128R, experienced menarche at 11 years old, underwent irregular menstrual cycle (2–12 months per menstrual cycle) since 13 years old, and suffered amenorrhea at 24 years of age." (PMID 35174157, 2021).
End Stage Liver Disease (1 paper, 2022). Final stage of a liver disease when the liver failure is irreversible and LIVER TRANSPLANTATION is needed. "Moreover, a prominent increase in HSF2BP expression was observed in the livers of patients with the benign end-stage liver disease compared with the normal livers." (PMID 36167792, 2022).
glioblastoma (1 paper, 2023). The most malignant astrocytic tumor (WHO grade IV). "Among these patients, WWOX may be inaccessible for its partners and does not manifest its anti-cancer activity, which was proposed in the literature but not regarding glioblastoma or concerning POLE4 and HSF2BP." (PMID 37781246, 2023).
lentivirus infection (1 paper, 2022). Virus diseases caused by the Lentivirus genus. "The HSF2BP knockdown efficiency in NCI-H209 and A549 cells after lentivirus infection was confirmed by western blot analysis." (PMID 35435115, 2022).
liver diseases (1 paper, 2023). "The feasibility of HSF2BP-targeted treatment in ER stress-related liver disease deserves future research." (PMID 36964632, 2023). "HSF2BP is a promising hepatoprotective factor and deserves further research for its potential prophylactic and therapeutic effects in a variety of ER stress-related liver diseases." (PMID 36964632, 2023). "In this regard, the role of HSF2BP in other liver diseases, and whether there is a mechanism independent of HSF2, warrant investigation." (PMID 36964632, 2023). "However, the role of HSF2BP in other liver diseases has not been elucidated." (PMID 36964632, 2023).
teratozoospermia (1 paper, 2022). "In the present study, a missense variant characterized as moderate impact was also identified on HSF2BP in teratozoospermic individuals suggesting a role of this interaction in teratozoospermia that requires further investigation." (PMID 36140773, 2022).
trisomy (1 paper, 2022). A chromosomal abnormality consisting of the presence of one chromosome in addition to the normal diploid number. "To separate the homologs, we successfully established three corrected disomy 21 iPS cell lines by introducing the Cre-loxP system into chromosome 21 at intron 3 of the HSF2BP gene in the original trisomy 21 iPSCs using CRISPR-Cas9 technology." (PMID 35637312, 2022).
cancer (11 papers, 2019 to 2024). A tumor composed of atypical neoplastic, often pleomorphic cells that invade other tissues. "Intriguingly, recent studies found that the somatic cells overexpressing HSF2BP were sensitive to DNA interstrand crosslink, which increased cancer susceptibility." (PMID 35174157, 2021). "For example, we previously found that HSF2BP, when produced ectopically in somatic cancer cells, interferes with the role of BRCA2 in DNA interstrand crosslink repair by causing its degradation." (PMID 34326328, 2021). "HSF2BP is transcribed in human cancer cell lines and overexpressed in some tumor samples." (PMID 35734584, 2022). "Besides, HSF2BP has been reported to be transcribed in all cultured human cancer cell lines and elevated in some tumor samples." (PMID 36167792, 2022). "Therefore, HSF2BP is expected to be a promising target for cancer treatment." (PMID 35435115, 2022). "A recent search for new BRCA2 partners identified HSF2BP (also named MEILB2) as another BRCA2-binding protein, endogenously expressed in meiotic cells, and ectopically produced in cancer cells." (PMID 34356684, 2021). "We identified HSF2BP as another BRCA2-binding protein, endogenously expressed in meiotic cells, and ectopically produced in cancer cells." (PMID 34326328, 2021). "In addition, BRCA2 acts as a tumor suppressor in mitotic HR, and HSF2BP can bind to BRCA2 and mediate its recombination localization, thereby promoting cancer development by interfering with the mitotic HR pathway." (PMID 35435115, 2022).
tumor (3 papers, 2022 to 2024). "Compared with shCtrl group, Ki67 expression was down-regulated in the sh-HSF2BP group, which indicated that HSF2BP knockdown inhibited the tumor growth in vivo." (PMID 35435115, 2022). "The high expression of HSF2BP is positively correlated with tumor stage, indicating that HSF2BP has an important effect on the progression of LUAD." (PMID 35435115, 2022). "Compared with that in normal tissues, the HSF2BP mRNA levels were markedly higher in the tumor tissues." (PMID 35435115, 2022). "Clinical correlation analysis revealed that tumor stage was positively correlated with high HSF2BP expression." (PMID 35435115, 2022). "HSF2BP knockdown inhibited the tumor formation, tumor growth rate and tumor volume." (PMID 35435115, 2022). "To date, the expression and biological function of HSF2BP in tumor tissues have not been specifically studied." (PMID 35435115, 2022). "Combined with a clinical correlation analysis, the HSF2BP expression in LUAD tissues was positively correlated with tumor stage, but not with other clinicopathological parameters." (PMID 35435115, 2022).
HSF2BP also shares sentences with these, for which no sentence is quoted: infertile (2 papers); breast tumor (1); cardiovascular disease (1); coronary artery disease (1); lung adenocarcinoma (1); Obesity (1); ovarian carcinoma (1); Premature ovarian insufficiency (1); sterility (1).